USP17L2 (ubiquitin specific peptidase 17 like family member 2)
Description:
Deubiquitinating enzyme that removes conjugated ubiquitin from specific proteins to regulate different cellular processes. Regulates cell proliferation by deubiquitinating and inhibiting RCE1 thereby controlling the small GTPases NRAS and HRAS localization and activation. In parallel, mediates deubiquitination of CDC25A, preventing CDC25A degradation by the proteasome during the G1/S and G2/M phases promoting cell-cycle progression. Also regulates cell proliferation and apoptosis through deubiquitination of SUDS3 a regulator of histone deacetylation. Through activation of the Rho family GTPases RAC1A, CDC42 and RHOA, regulates cell migration. Through the cleavage of 'Lys-48'- and 'Lys-63'-linked polyubiquitin chains of the cytoplasmic innate immune receptors RIGI and IFIH1 stimulates the cellular response to viral infection.
Synonyms: USP17; DUB-3; DUB3
Tractability: No criterion of Open Targets' tractability assessment is met for any kind of drug.
Target class: Cysteine protease; Cysteine protease CA clan; Protease; Enzyme; Cysteine protease C19 family
Gene: Protein-coding gene on chromosome 8 (12,136,435 to 12,138,849, reverse strand). Ensembl gene ENSG00000223443.
Subcellular location: Nucleus; Endoplasmic reticulum
Pathways (Reactome):
Metabolism of proteins: Ub-specific processing proteases
Signal Transduction: RAS processing
Gene Ontology:
Molecular function: cysteine-type deubiquitinase activity; protein binding
Biological process: CAAX-box protein processing; negative regulation of GTPase activity; negative regulation of protein processing; negative regulation of protein targeting to membrane; positive regulation of GTPase activity; positive regulation of MDA-5 signaling pathway; positive regulation of RIG-I signaling pathway; protein deubiquitination; protein K48-linked deubiquitination; protein K63-linked deubiquitination; regulation of cell migration; regulation of cell population proliferation; regulation of defense response to virus by host; regulation of G2/MI transition of meiotic cell cycle; regulation of ruffle assembly; MAPK cascade; regulation of apoptotic process
Cellular component: endoplasmic reticulum; endoplasmic reticulum membrane; nucleus; cytosol
Genetic constraint (gnomAD): Loss-of-function variants: 29 observed, 21.69 expected, observed/expected ratio (o/e) 1.34, 90% interval 0.99 to 1.79. The synonymous counts are far from expectation, so gnomAD's model fits this gene poorly and the ratio says little. Missense variants: 547 observed, 402.5 expected, observed/expected ratio (o/e) 1.36, 90% interval 1.27 to 1.46. Synonymous variants: 224 observed, 155.61 expected, observed/expected ratio (o/e) 1.44, 90% interval 1.29 to 1.61.
Homologues: Paralogues in human: USP17L3 (97% identical), USP17L1 (96% identical), USP17L4 (96% identical), USP17L8 (96% identical), USP17L11 (95% identical), USP17L17 (95% identical), USP17L20 (95% identical), USP17L22 (95% identical), USP17L18 (95% identical), USP17L19 (95% identical), USP17L24 (95% identical), USP17L25 (95% identical), and 59 more.
Diseases named in the same sentence as USP17L2 in open-access papers:
USP17L2 is named in the same sentence as 24 diseases in open-access papers, as found by Europe PMC text mining. Sharing a sentence is not in itself a finding about the gene and the disease. The quoted sentences say what the papers report.
breast carcinoma (24 papers, 2014 to 2025). "DUB3 (official symbol USP17L2) was shown to promote breast cancer invasion and metastasis via stabilizing Snail1 in a CDK4/6 activity-dependent manner." (PMID 32968046, 2020). "Additional evidence demonstrated that pristimerin increases miR-542-5p levels and that this miRNA directly targets ubiquitin-specific-processing protease 17-like protein 2 (USP17L2, also referred to as DUB3), which promotes migration, invasion, and metastasis of breast cancer by stabilizing SNAI1." (PMID 33066509, 2020). "Furthermore, USP17L2 (known as DUB3) deubiquitylates and is responsible for the stabilization of Cdc25A to promote oncogenic transformation in human breast cancers." (PMID 25972356, 2015).
cancer (26 papers, 2006 to 2025). A tumor composed of atypical neoplastic, often pleomorphic cells that invade other tissues. "Several other DUBs discussed in this review including DUB3/USP17L2, USP3, and POH1/PSMD14 have been implicated in cancer for their abilities to regulate migration, invasion, and drug resistance." (PMID 32708614, 2020).
tumor (22 papers, 2011 to 2025). "Cdc25A is highly expressed in tumor tissues and can be stabilized by ubiquitin-specific peptidase 17 like family member 2 (Dub3)." (PMID 36613989, 2022). "Deubiquitinases USP9X, Ku70, JOSD1, DUB3/USP17L2, and USP13 have been described to stabilize Mcl-1, promote tumor cell survival and suppress apoptosis." (PMID 35301297, 2022). "In paired cfDNA and primary tumor samples, focal high-level DNA amplifications clustered in numerous chromosome arms, some of which harbored genes with oncogenic potential, including USP17L2 (DUB3), BRF1, MTA1, and JAG2, were identified." (PMID 26453190, 2015).
USP17L2 also shares sentences with these, for which no sentence is quoted: ovarian carcinoma (8 papers); lung carcinoma (5); prostate carcinoma (5); breast tumor (3); colorectal cancer (3); hepatocellular carcinoma (3); triple-negative breast carcinoma (3); lung adenocarcinoma (2); non-small cell lung carcinoma (2); colitis (1); colon cancer (1); endometrial cancer (1); gastric cancer (1); glioblastoma (1); glioma (1); liver cancer (1); melanoma (1); metastatic carcinoma (1); nut midline carcinoma (1); renal carcinoma (1); rhabdomyosarcoma (1).